OR5AS1 (olfactory receptor family 5 subfamily AS member 1)
Description:
Odorant receptor.
Synonyms: OR11-168
Tractability: Small molecule: it belongs to a druggable protein family. Antibody: UniProt places it where antibodies can reach, with medium confidence; UniProt predicts a signal peptide or a membrane-spanning region; its Gene Ontology location is reachable by antibodies, with medium confidence.
Gene: Protein-coding gene on chromosome 11 (56,027,654 to 56,038,191, forward strand). Ensembl gene ENSG00000181785.
Subcellular location: Cell membrane
Pathways (Reactome):
Sensory Perception: Expression and translocation of olfactory receptors
Gene Ontology:
Molecular function: protein binding; odorant binding; olfactory receptor activity; G protein-coupled receptor activity
Biological process: sensory perception of smell; detection of chemical stimulus involved in sensory perception of smell; G protein-coupled receptor signaling pathway
Cellular component: plasma membrane; membrane
Genetic constraint (gnomAD): Missense variants: 327 observed, 260.55 expected, observed/expected ratio (o/e) 1.26, 90% interval 1.15 to 1.38. Synonymous variants: 128 observed, 99.54 expected, observed/expected ratio (o/e) 1.29, 90% interval 1.11 to 1.49.
Homologues: Orthologues: chimpanzee OR5AS1 (98% identical), dog OR5AS1 (85% identical), rabbit OR5AS1 (82% identical), mouse Or5as1 (78% identical), rat Or5as1 (77% identical), guinea pig OR5AS1 (70% identical). Paralogues in human: OR5I1 (53% identical), OR5AP2 (52% identical), OR5AR1 (52% identical), OR5W2 (51% identical), OR5C1 (50% identical), OR5AU1 (49% identical), OR9I1 (49% identical), OR5B21 (49% identical), OR8D4 (49% identical), OR8J2 (48% identical), OR8U1 (48% identical), OR5A1 (48% identical), and 84 more.